EGFR (epidermal growth factor receptor)
Diseases named in the same sentence as EGFR in open-access papers (continued):
Sharing a sentence is not in itself a finding about the gene and the disease.
cancer (continued). "With 10 identifiers, we observed that these genes interacted with stemness genes such as SOX-2 and NANOG, genes important in cancer pathways such as STAT3, CTNNB1, EGFR, TNF, and CASP3, and immune genes such as IL2 and CD4." (PMID 34685742, 2021). "Since EGFR can regulate cellular signaling involved in EMT, it is feasible that miR-133-3p modulates EMT in cancer." (PMID 33435156, 2021). "EGFR and HER2 are overexpressed membrane proteins and therapeutic targets in many different types of cancer, for instance, in breast and gastric cancers." (PMID 34831465, 2021). "ESR1, TOR1AIP1, STAT1, COL1A1 were identified as high expression, while EGFR, AR, GATA2 were identified as a low expression in both cancer types." (PMID 33907495, 2021). "EGFR functions as a cytoplasmic-membrane-bound RTK that induces growth and survival signals in cancer." (PMID 34884765, 2021). "This research demonstrated that whereas miR-7-5p inhibited cancer growth and metastasis through the management of EGFR, LINC00240 suppressed cancer metastasis by acting as a sponge for miR-7-5p." (PMID 33422052, 2021). "Both EGFR and VEGFR2 are critical regulators in cancer progression, with the upregulation of VEGFA-VEGFR2 signaling pathways contributing to the resistance to EGFR-TKI treatment." (PMID 34680445, 2021). "One study demonstrated diverse oncogene-addicted cancer cells and CSCs (lung, melanoma, leukemia, breast) showed selective reliance on OXPHOS and resistance to EGFR-TKIs." (PMID 34322664, 2021). "In cervical cancer, EGFR signaling can be affected by Hippo/YAP pathway and eventually influence cancer progression." (PMID 34646755, 2021). "EGFR and ERBB are two major biomarkers and drug targets in several diseases, including various forms of cancer." (PMID 34439912, 2021). "eHSP90, together with its co-chaperone CDC37, also interacts with the family of ERBB receptors, including EGFR or HER2, to promote cancer cell motility and invasion." (PMID 33544155, 2021). "The figure showed that the anti-NSCLC effects of the six C21 steroidal saponins mainly involved pathways in cancer, including HIF-1 signaling, PI3K-Akt signaling, VEGF signaling, EGFR tyrosine kinase inhibitor resistance, and Ras signaling." (PMID 33994999, 2021). "Crystal structure analysis have revealed that these antibodies bind to domain III of EGFR and thereby inhibit binding of EGF, which in turn blocks the signaling and proliferation of cancer cells." (PMID 33707468, 2021). "In cancer, several ADAM proteases promote malignancy by EGFR transactivation, supporting epithelial to mesenchymal transition (EMT) via cleavage of E-cadherin." (PMID 33672843, 2021). "Most known cancer genes have been found through primary cytogenetic analyses, although sequencing of cancer genomes has revealed new cancer genes including BRAF, EGFR, ERBB2, PIK3CA, PPP2R1A, and JAK2." (PMID 34298667, 2021). "Exosomal miR‐1169 and miR‐260 were identified as potential candidates, which contain specific characteristics that can distinguish between wild‐type EGFR and mutant EGFR NSCLC patients in early‐stage cancers." (PMID 33682961, 2021). "Receptor tyrosine kinases (RTK) like the ERBB receptor family, including EGFR/ERBB1, ERBB2/NEU, ERBB3, and ERBB4, are important regulators of skin homeostasis and their dysregulation often results in cancer, which makes them attractive therapeutic targets." (PMID 33786987, 2021). "Several ANO1-related signaling pathways, including EGFR-mediated AKT/SRC/ERK1/2 and Ras-Raf-MEK-ERK1/2, have been reported in cancer development." (PMID 34281152, 2021). "Taken together, our study revealed that EGFR promotes MOB1 phosphorylation and suppresses the Hippo pathway, leading to aberrant YAP/TAZ activation in cancers harboring EGFR alterations." (PMID 34725466, 2021). "Upon EGFR signalling, pyruvate kinase M2 (PKM2) was activated and it stimulated the gene expression and cancer cell growth by binding to FOSL1 or ANTXR2 promoter." (PMID 34298701, 2021).
cancer (continued). "The aptamers specifically recognized surface cancer markers, such as EGFR in breast cancer and PSMA in prostate cancer, thus guiding the sEVs to cancer cells." (PMID 33791224, 2021). "Epidermal growth factor receptor (EGFR), belonging to the ErbB family, plays an important role in the molecular pathology of NSCLC and other cancers." (PMID 34112110, 2021). "Truly, a wealth of information illustrates that Src regulates EGFR, PKB and ERK‐1/2 in multiple cancers." (PMID 34318593, 2021). "Various studies have suggested that panobinostat is closely related to the suppression of cancer progression that is mediated by the regulation of several signaling pathways, including STAT3, EGFR, and RAF/ERK." (PMID 34073071, 2021). "MiR-146b from MSC exosomes binds to epidermal growth factor receptor (EGFR) mRNA, and eventually reduced growth, migration, and invasion of cancer cells in culture." (PMID 34020704, 2021). "The research results showed that GE11-CUR/ICG-LPs, together with PDT, could induce the apoptosis of cancer cells by promoting ROS generation and cell cytoskeleton disruption by the increased stimulation of apoptotic signaling pathways and the inhibition of the EGFR-mediated PI3K/AKT pathway." (PMID 34683855, 2021). "Moreover, a comprehensive understanding of pathways obtained through multiomic analyses may clarify the detailed characteristics of TMEs and the spatial compartmentalization of EREG/EGFR signaling and crucial related molecules, thus providing new insights into treatment against cancer development." (PMID 34884633, 2021). "Recently, a novel bispecific anti-EGFR DARPin fused with the inhibitory prodomain of ADAM17 was shown to decrease cell proliferation and migration of EGFR-dependent cancer cells." (PMID 33808165, 2021). "The GDSC data set had a total of 47 unique drugs with ten targets, including EGFR, IGF1R, HDAC1, PARP2, AURKA, and BRAF, as well as their sensitivities across 224 cancer cell lines." (PMID 33795761, 2021). "EGFR activation provokes the downstream activation of pathways, including ERK and AKT, leading to cancer cell survival and proliferation." (PMID 33801379, 2021). "We also noted that the cancer line BFTC905, even though it robustly expressed both target antigens, was only marginally killed by the EGFR and CD44v6 CAR T-cells from several donors." (PMID 34868059, 2021). "The cytotoxic effect of ATZ-502 was demonstrated in several cancer cells by blocking the nuclear translocation of pSTAT3, STAT3, EGFR, and ErbB2 by karyopherin β1." (PMID 33801927, 2021). "EGFR is overexpressed in ~90% of HNSCC patients and drives the cancer through downstream MAPK and phosphatidylinostiol-3-kinase (PI3K)/AKT/mammalian target of rapamycin (mTOR) signaling." (PMID 33799513, 2021). "Recent studies have reported that axitinib serves as a multi-receptor tyrosine kinase inhibitor to treat multiple cancers, and axitinib inhibits the VEGF receptor, platelet-derived growth factor receptor, and epidermal growth factor receptor." (PMID 34497633, 2021). "It was elucidated that 44 integrated HDAC and EGFR/HER2 pathway inhibition, blocked and inhibited MET- and AXL-mediated signaling, and reduced cancer cell migration." (PMID 33946916, 2021). "EGFR and HER2 represent important targets for the design of new drugs against different types of cancer, and recently, differences in affinity depending on active or inactive states of EGFR or HER2 have been identified." (PMID 34451888, 2021). "Previously, we reported that (E)-N-(5-benzylthiazol-2-yl)-3-(furan-2-yl) acrylamide (aminothiazole, ATZ-502) showed cytotoxic effects in several cancer cells by blocking the function of KPNB1 with pSTAT3, STAT3, EGFR, and ErbB2." (PMID 33801927, 2021).
cancer (continued). "Apparently, the results confirm that EWI‐2 indeed contributes to the suppressed activation of EGFR phosphorylation and suggest that the EWI‐2 is likely required for the suppression of EGFR‐mediated cancer cell motility." (PMID 33605506, 2021). "Epidermal growth factor receptor (EGFR), a transmembrane receptor of extracellular protein ligands, is deregulated in many cancer types." (PMID 34931923, 2021). "Both HER2 as well as EGFR are frequently overexpressed in breast cancer, amplify the RAS signaling pathway and are therapeutically targeted to treat this cancer type." (PMID 33801965, 2021). "In this study we sought to determine the anti-cancer effects of DPT on HCC827GR cells, which are resistant to gefitinib (EGFR-TKI) due to regulation of EGFR and MET and their related signaling pathways." (PMID 33746190, 2021). "Lapatinib is an oral reversible dual tyrosine kinase inhibitor that blocks EGFR and HER2, both frequently overexpressed in human cancer." (PMID 33918490, 2021). "In recent years, intensive research has been dedicated to the Epidermal Growth Factor Receptor (EGFR) due to its significant role in the pathogenesis of malignant tumors." (PMID 33435596, 2021). "Our study supports further exploring PDHK targeting in combination with EGFR TKI, ionizing radiation or other relevant therapies, as promising options targeting the essential mechanisms of cancer progression." (PMID 33668151, 2021). "Note that the epidermal growth factor receptor (EGFR), which is often overexpressed in cancer cells, has been recently reported as a potential target for platinum (II)-terpyridine compounds." (PMID 34578470, 2021). "More importantly, the HOIP inhibitor, HOIPIN-8, inhibited EGFR-mediated NF-κB activation and cell proliferation of A431, MCF-7, and MDA-MB-231 cancer cells." (PMID 34769306, 2021). "According to modern data, the incidence of dermatological toxicity (DT) against the background of treatment of various cancers by inhibitors of tyrosine kinase receptors of epidermal growth factor (EGFR, epidermal growth factor receptor) reaches 90-95%." (PMID 33794894, 2021). "The first-generation reversible epidermal growth factor receptor (EGFR) inhibitors, gefitinib (GEF) and erlotinib are the anti-cancer drugs that target EGFR." (PMID 33746190, 2021). "Src kinase is a downstream target of EGFR, and correlation analysis using the NCI60 database pointed to a role of EGFR in cardenolide glycoside-induced cancer cell death." (PMID 34025398, 2021). "These nanoparticles can effectively enter cancer cells using its epidermal growth factor receptor (EGFR) antibody, since cancer cells have overexpressed EGFR." (PMID 34685230, 2021). "Inhibition of FGFR or EGFR, in combination with the RET inhibitor sorafenib, significantly improved response to treatment in human cancer cell lines harboring the RET-HIF5B fusion protein." (PMID 34068954, 2021). "A preclinical investigation demonstrated that EGFR-TKI administration not only decreased the viability of cancer cells, but also increased IL-6 production from cancer cells." (PMID 33466795, 2021). "Both Dovitinib and BGJ398 have been used in clinical trials for several cancers with defined FGFR genetic alterations, while PD166866 is a highly selective inhibitor towards FGFR1 and other kinases such as c-Src, PDGFR, and EGFR." (PMID 33456711, 2021). "More specifically, z-guggulsterone altered the Bcl-2 family proteins and regulates FXR, NF-κB signaling, MAPK signaling, EGFR, and Jak2-STAT3 signaling pathways in various cancer cells." (PMID 33488300, 2021). "Collectively speaking, the increased levels of LLGL2, EGFR and decreased level in CDH1, recorded in the current study, promote EMT and cancer cell migration in BC." (PMID 33073304, 2021). "It is also noteworthy that the EGFR signaling pathway has crosstalk with the Hippo/YAP pathway, which positively regulating the YAP oncogenic function in various cancers including NSCLC." (PMID 34113560, 2021).
cancer (continued). "These functions have an effect on cancer cells, as AP2M1 regulates insulin-like growth factor-1 receptor (IGF1R) in prostate cancer and EGFR internalization in bladder cancer." (PMID 34565296, 2021). "Across a broad panel of oncogene-driven pre-clinical models, we observed a highly conserved transcriptomic signature following kinase inhibition including induction of IFN-target genes, which was most pronounced in EGFR-driven and BRAF-driven cancers." (PMID 34535668, 2021). "Immune evasion and growth factor dependence are two hallmarks of cancer, which can be targeted by ICI and CIMAavax-EGF or anti-EGFR MAbs." (PMID 34211836, 2021). "For instance, epidermal growth factor (EGF) is a ligand of EGFR, a proto-oncogene that activates downstream kinases, such as FAK, to regulate cell adhesion site dynamics, thus promoting cancer growth, migration, and metastasis." (PMID 33854965, 2021). "Epidermal growth factor receptor (EGFR), Insulin-like growth factor -1 receptor (IGF-1R), and Vascular Endothelial Growth Factor -A (VEGF-A) are overexpressed in various human cancers including CRC." (PMID 34638601, 2021). "Actually, EGFR and VEGF are known as receptors that transduce multiple downstream signaling pathways in several cancers." (PMID 34067437, 2021). "Signaling pathway analysis revealed that these MM-SE genes were highly enriched in key pathways related to cancer development and progression, including Ras, p38 MAPK, and EGFR signaling pathway." (PMID 33579893, 2021). "Genes such as EGFR, PIK3CA, DROSHA, MDM4, and APC were located inside recurrently aberrant regions, while other known cancer-genes such as NF1, MET and mTOR were identified as cis-genes and located outside the most recurrently altered regions." (PMID 34625038, 2021). "In TNBC cells, PGRMC1 plays a prominent role in regulating the growth of cancer cells by altering the PI3K/AKT/mTOR and EGFR signaling mechanisms." (PMID 34746100, 2021). "It was reported that EGFR signalling enhances IRES-mediated translation of Sp1 during tumorigenesis, and Sp1 accumulates in cancer cells." (PMID 33597819, 2021). "Beyond an inhibition of the EGFR-signaling cascade, anti-EGFR IgG1-antibodies induce antibody-dependent, cell-mediated cytotoxicity (ADCC) in HNSCC and, therefore, act as an anti-cancer immunotherapeutic agent itself." (PMID 33718186, 2021). "Increased expression of VEGFA, PGE2S, COX2, EGFR, and NANOG in cancer cells was characteristic for the increase of resistance." (PMID 33671869, 2021). "Neuropilin-1 (NRP1, BDCA-4) induces a c-Jun N-terminal kinase (JNK)-dependent signaling cascade that leads to the upregulation of EGFR or IGF1R, thereby promoting cancer cell growth." (PMID 33732282, 2021). "EGFR (also known as ErbB1 and HER1), ERBB2 (HER2/neu and HER2), ERBB3 (HER3), and ERBB4 (HER4), members of the (EGFR)/(ERBB) family, are known among the most important cancer molecular targets." (PMID 34803458, 2021). "Thus, VF16 could be developed as a promising new anti-cancer drug targeting EGFR-TK." (PMID 33921332, 2021). "As with other cancer types, CRC is also treated with targeted therapy, prepared for affecting predominant markers, such as VEGFA and EGFR." (PMID 35053185, 2021). "In combination with radiotherapy, other EGFR antibodies IMC-C225 (cetuximab, Erbitux), Thermacin h-R3 (Cimaher) based on the given principle are getting quite successful in treating HNC cancer." (PMID 34490084, 2021). "This immune-droplet digital polymerase chain reaction (iddPCR) amplification method enabled the multiplexed profiling of EV proteins, e.g. EGFR, EPCAM, PD-L1, CD4, CD8, GZMB, TCF7 derived from cancer cell lines." (PMID 34855021, 2021).